NLRP3 (NLR family pyrin domain containing 3)
Diseases named in the same sentence as NLRP3 in open-access papers (continued):
Sharing a sentence is not in itself a finding about the gene and the disease.
Hyperglycemia (continued). "The NLRP3 inflammasome is involved in the regulation of inflammation induced by various non-infectious factors, such as lipid accumulation, oxidative stress associated with hyperglycemia, and hyperlipidemia." (PMID 40406487, 2025). "In human umbilical vein endothelial cells (HUVECs) and in diabetic mouse atherosclerotic lesions, hyperglycemia was associated with the increased expression of endothelial adhesion molecules—a process that was significantly attenuated by NLRP3 knockdown or IL-1 receptor antagonism." (PMID 40648980, 2025). "Moreover, hyperglycemia activated the NLRP3/caspase-1/GSDMD axis to cause pore formation, where GSDMD further aggravated pyroptosis in human retinal pericytes." (PMID 39253076, 2024). "Overexpression of SETD8 reduced inflammation by decreasing the activation of the NOD-like receptor pyrin domain 3 (NLRP3) inflammasome and the expression of microtubule-affinity regulating kinase 4 caused by hyperglycemia in human umbilical vein endothelial cells (HUVECs)." (PMID 38645427, 2024). "OxLDLs and high mobility group box protein 1, two agonist ligands of receptor for advances glycation endproducts (RAGE), have also been linked to NLRP3 activation which occurs in parallel with the atherosclerotic process in conjunction with hyperglycemia-induced ROS overproduction." (PMID 37175869, 2023). "Besides fatty acids, ROS and AT-derived DAMPs, hyperglycemia and endoplasmic reticulum (ER) stress in AT and pancreas have been associated with NLRP3 inflammasome priming." (PMID 37239938, 2023). "Accordingly, we hypothesized that P2X7 receptor expression is strongly activated in H9C2 cells with hyperglycemia injury, causing NLRP3/caspase-1-mediated pyroptosis." (PMID 37685976, 2023). "Hyperglycemia is associated with both conditions of oxidative stress and inflammatory state and promotes mitochondrial metabolism in β cells which enhances the production of ROS, thus inducing NLRP3 inflammasome activation and then IL-1β production." (PMID 35276849, 2022). "In this study, we hypothesized that UCP2 deficiency enhances NLRP3 inflammasome activation after hyperglycemia-exacerbated cerebral I/R damage." (PMID 33735403, 2021). "Therefore, this study focused on the effect of UCP2 deficiency on the expression of NLRP3 inflammasome components in neurons in the context of hyperglycemia-exacerbated cerebral I/R damage." (PMID 33735403, 2021). "The NLRP3 inflammasome can aggregate and produce a variety of inflammatory mediators when stimulants are detected, and autophagy is considered an effective regulator of NLRP3 inflammasome activation in hyperglycaemia‐associated vascular complications." (PMID 34180143, 2021). "Furthermore, UCP2 deficiency enhanced NLRP3 inflammasome activation in neurons in the context of hyperglycemia-exacerbated cerebral I/R damage." (PMID 33735403, 2021). "Moreover, UCP2 deficiency enhanced NLRP3 inflammasome activation in neurons when cerebral I/R damage was exacerbated by hyperglycemia." (PMID 33735403, 2021). "Furthermore, UCP2 deficiency promoted NLRP3 inflammasome activation under hyperglycemia-exacerbated cerebral I/R damage." (PMID 33735403, 2021). "Furthermore, UCP2 deficiency enhanced NLRP3 inflammasome activation after hyperglycemia-exacerbated cerebral I/R damage in vivo and in vitro." (PMID 33735403, 2021). "In the current study, we hypothesized that LBE supplementation could ameliorate hyperglycemia-induced renal inflammation by regulation of NLRP3-inflammasome associated hyperinflammation in an in vivo diabetic model." (PMID 32050658, 2020). "NLRP3 is the largest inflammasome subset in cells and can be activated by both pathogenic microorganisms (such as viruses, fungi, and bacteria) and cell metabolic products (extracellular ATP, crystalline uric acid, hyperglycemia, hyperlipidemia, etc.)." (PMID 30704457, 2019).
Hyperglycemia (continued). "Thus, TRPM2 may represent a new target for ameliorating T2DM caused by hyperglycemia-induced oxidative stress and subsequent NLRP3 inflammasome activation." (PMID 36378463, 2023). "NLRP3 inflammasome activation requires the following steps: pattern recognition receptors recognize pathogen-related molecular patterns (PAMPs, such as viruses or bacteria) or damage-associated molecular patterns (DAMPs, such as hyperglycemia or hyperlipidemia) and activate NF-κB signaling." (PMID 34055976, 2021). "Hence, this study was aimed to investigate whether high concentration of glucose (HG), which mimics the hyperglycemia environment, could initiate vascular calcification through NLRP3/IL-1β inflammasome and the underlying mechanism." (PMID 31938471, 2020). "For example, MSC-derived EVs mitigate hyperglycemia-induced inflammation through miRNA-mediated suppression of NF-κB and NLRP3, while PDGF-BB hydrogels compensate for impaired PDGF signaling observed in diabetic wounds." (PMID 41328337, 2026). "Chronic hyperglycemia exacerbates NLRP3 activity, perpetuating the release of pro-inflammatory cytokines like IL-1β and IL-18, and inhibiting angiogenesis 165,166." (PMID 41328337, 2026). "Taken together, these data suggest that rTMD1 confers general anti‐inflammatory, pro‐repair benefits and, in the diabetic cornea, specifically corrects hyperglycemia‐sensitive HMGB1/TLR4/NLRP3 signaling to facilitate reepithelialization." (PMID 41503166, 2026). "We particularly focus on how disease-specific triggers in kidney pathologies such as hyperglycemia, uric acid, lipotoxicity, and ischemia reperfusion instrumentalize NLRP3 to drive irreversible renal injury." (PMID 41357229, 2025). "ROS/RNS, hyperglycemia, and ischemia can prime the NLRP3 inflammasome, which produces cytokines such as IL-1β and IL-18, promoting ED." (PMID 40227195, 2025). "DHAP accumulation under hyperglycemia activates mTORC1/ROS/NLRP3 pathway, inducing podocyte pyroptosis." (PMID 41009556, 2025). "InflammaProbe-2was able to visualize NLRP3 inflammasomes in ARPE-19 cells treatedunder hyperglycemia as well as inflammatory conditions." (PMID 40758602, 2025). "Studies have shown that ULK1 can inhibit the activity of the NLRP3 inflammasome in the pyroptosis pathway potentially aiding in mitigating the harmful effects of hyperglycemia-induced oxidative stress and inflammation in diabetic wounds." (PMID 40750912, 2025). "Hyperglycemia induces the assembly and activation of the NLRP3 inflammasome, prompting the release of numerous inflammatory factors, such as IL-1β and IL-18." (PMID 41394140, 2025). "Hyperglycemia and bacterial colonization in diabetic wounds aberrantly activate Nod-like receptor protein 3 (NLRP3) in macrophages, resulting in extensive inflammatory infiltration and impaired wound healing." (PMID 39850366, 2025). "The priming phase, triggered by hyperglycemia, oxidative stress, and lipotoxicity, activates NF-κB signaling, leading to increased NLRP3 expression and the production of pro-IL-1β and pro-IL-18." (PMID 40427455, 2025). "Dyslipidemia and hyperglycemia boost mitochondrial ROS, activating NLRP3 inflammasomes and destabilizing plaques." (PMID 40727914, 2025). "Inhibition of NLRP3 ameliorated the hyperglycemia-induced inflammation and decline in steroidogenic ability." (PMID 40940788, 2025). "Further investigation demonstrated that NLRP3 mediates hyperglycemia-induced inflammation, and NLRP3 inhibition attenuated IL-1β activation and the decline in the steroidogenic capacity in the Leydig cells." (PMID 40940788, 2025). "Its activation involves a priming phase—triggered by hyperglycemia and OS—that upregulates NLRP3 and pro-inflammatory cytokines via NF-κB." (PMID 40429855, 2025). "Conversely, 3-MA enhanced the NLRP3 expression and IL-1β maturation, demonstrating autophagy’s essential role in suppressing NLRP3-mediated inflammation under hyperglycemia." (PMID 40940788, 2025).
Hyperglycemia (continued). "Studies have demonstrated that calcium influx, triggered by factors such as metabolic abnormalities (including hyperglycemia and hyperlipidemia) and oxidative stress, can directly activate the NLRP3 inflammasome and facilitate the release of IL-1β." (PMID 41301787, 2025). "Hyperglycemia also induces pro-inflammatory factors and expression of NLRP3 in ECs, increasing oxidative stress at mitochondrial level and apoptosis." (PMID 40227195, 2025). "Under hyperglycemia conditions, the activation of the NF-κB/NLRP3 pathway by TLR4 was generally carried out by stimulating its downstream myeloid differentiation primary-response protein-88 (MyD88) in DKD." (PMID 39000237, 2024). "Recent research has shown that knocking down NLRP3 can impede podocytes injury through reducing the hyperglycemia-induced production of mitochondrial ROS in renal mesangial cells and preventing lipid accumulation." (PMID 38542060, 2024). "GLP-1 RAs can additionally guard against hyperglycaemia-induced autoinflammatory damage, inhibiting NLR family pyrin domain-containing 3 (NLRP3) inflammasome formation and thereby conferring anti-pyroptotic effects on cardiomyocytes." (PMID 39200816, 2024). "ROS are generated by the nucleotide-binding domain leukin-rich repeat-containing family pyrin domain-containing 3 (NLRP3) inflammasomes, and which are activated by hyperglycemia." (PMID 38542060, 2024). "Hyperglycemia, hyperlipidemia, and hyperuricemia trigger the NLRP3 inflammasome, linking metabolic stress in DN to pro-inflammatory responses via IL–1β and IL–18." (PMID 38890983, 2024). "Hyperglycemia plays a role in stimulating and activating nucleotide-binding oligomerization domain (NOD)-like receptor pyrin domain 3 (NLRP3) and adaptor protein apoptosis-associated speck-like protein (ASC)." (PMID 37765083, 2023). "Blockade of NLRP3 inflammasome–mediated secretion of IL-1β in TET2-deficient immune cells using MCC950 suppressed the higher levels of IL-1β and increased hyperglycemia and IR in mice carrying TET2-deficient HSCs." (PMID 37071471, 2023). "Hyperglycemia triggers Nod-like receptor (NLR) family pyrin domain-containing 3 (NLRP3) overactivation, which promotes the maturation and release of IL-1β and IL-18." (PMID 37175496, 2023). "As part of the innate immune system, NLRP3 is also responsible for the chronic inflammation triggered by hyperglycemia." (PMID 37762961, 2023). "Hyperglycemia can also increase the production of reactive oxygen species (ROS), providing the second signal, called the activation signal, as well as initiating NLRP3 complex assembly and active IL-18 and IL-1β production." (PMID 37238986, 2023). "Prolonged hyperglycemia causes upregulation of TXNIP, a modulator of NLRP3, which in turn will activate inflammatory signaling pathways." (PMID 37762961, 2023). "In particular, hyperglycemia in streptozotocin (STZ)-induced or db/db diabetic mice can induce NLRP3 inflammasome activation in glomerular podocytes, resulting in podocyte loss and albuminuria." (PMID 37373116, 2023). "In summary, our research demonstrates that hyperglycemia activates the NLRP3 inflammasome signaling pathway, leading to cardiomyocyte pyroptosis." (PMID 37765083, 2023). "Hyperglycemia induced ROS generation which leads to the activation of NLRP3 inflammasome, thereby inducing lung injury." (PMID 36648717, 2023). "A study found that in diabetic mouse models, persistent hyperglycaemia can lead to macrophage dysfunction in which activation of NLRP3 inflammasome plays an important role." (PMID 38250736, 2023). "Studies utilizing cellular or animal models have demonstrated that, in the presence of hyperglycemia, NLRP3 induces endothelial inflammation." (PMID 37762961, 2023). "For example, hyperglycemia promoted cardiomyocyte pyroptosis by activating the AMPK-TXNIP/NLRP3 signaling pathway, and pyroptosis-associated TLR4 and NLRP3 inflammasome expression was increased in HG-treated H9C2 cardiomyocytes." (PMID 36387904, 2022).
Hyperglycemia (continued). "Autophagy has been demonstrated to suppress NLRP3 inflammasome, although this effect is disturbed by hyperglycemia." (PMID 35692570, 2022). "Hyperglycemia can damage mitochondria which resulting in ROS overproduction and activate NLRP3 inflammasome to injure myocardial cell." (PMID 35103095, 2022). "Previous studies have elucidated that the NLRP3 inflammasome is activated in the myocardium when exposed to hyperglycemia and pyroptosis which contributed to the development of DCM." (PMID 35498125, 2022). "In endothelial cells, ROS acts as a bridge between pathological stimuli such as ox-LDL, hyperglycemia, Ang II, and nicotine and the activation of the NLRP3 inflammasome." (PMID 36389728, 2022). "In DCM, hyperglycemia stimulates the activation of inflammasomes in nucleotide-binding oligomerization domain-like receptor protein 3 (NLRP3)." (PMID 35034587, 2022). "Hyperglycemia induces superimposed effects on caspase-1 in stroke, as specific NLRP3 inhibitor MCC950 showed stronger alleviation of BBB destructions in hyperglycemic stroke than stroke without hyperglycemia." (PMID 35370546, 2022). "3TC attenuated LPS-induced pro-inflammatory, pro-apoptotic, and pro-pyroptosis effects under hyperglycemia by targeting the P2X7/NLRP3 pathway, preventing tissue damage, cell apoptosis, cytokine production, and inflammatory signaling pathway activation." (PMID 35410316, 2022). "What’s more, In the diabetic heart, the NLRP3 inflammasome responds to hyperglycemia-induced toxicity and initiates the progression of pyroptosis." (PMID 35355717, 2022). "Another study showed that hyperglycemia significantly increased the expression of NLRP3, ASC, and proinflammatory cytokines in high glucose-induced RMECs and diabetic rat retinas." (PMID 35813208, 2022). "Epac1 (a downstream mediator of β-adrenergic receptors) agonist and/or NLRP3 siRNA can effectively reduce hyperglycemia-induced increases in TLR4, HMGB1, cleaved caspase-1, and IL-1β in RECs." (PMID 35813208, 2022). "Puerarin regulates NLRP3 inflammation through autophagy and has protective effects on chronic vascular diseases induced by hyperglycemia." (PMID 36358493, 2022). "Autophagy is deemed to be an efficient regulator of NLRP3 inflammasome activation in hyperglycemia-related vascular complications." (PMID 36358493, 2022). "During DCM, the NLRP3 inflammasome aggravates cardiac fibrosis and promotes hyperglycemia-induced CF activation." (PMID 36111168, 2022). "In DM, hyperglycemia changes endothelial permeability by inducing endothelial cell pyroptosis in an NLRP3 inflammasome-dependent manner, and inhibition of the NLRP3 inflammasome ameliorates endothelial barrier dysfunction." (PMID 36111168, 2022). "In a DCM mouse model induced by streptozotocin (STZ), inhibiting NLRP3 inflammasome activation remarkably improves cardiac function and decreases myocardial hypertrophy induced by hyperglycemia." (PMID 36111168, 2022). "Hyperglycemia and high free fatty acid levels also activate NLRP3 inflammatory bodies that activate reactive oxygen species pathways." (PMID 35651872, 2022). "There are convincing data suggesting that NLRP3 inflammasome is fundamental in the deleterious effect observed in chronic hyperglycemia and oxidative stress." (PMID 35276849, 2022). "A recent study reported that empagliflozin reduced the diabetic pancreatic tissue from hyperglycemia-induced damage of db/db mice via the suppression of the NLRP3/caspase-1/GSDMD pathway." (PMID 35265148, 2022). "Although hyperglycemia has been proved to be one of the triggers of NLRP3 inflammasome activation, the specific details of the relationship between hyperglycemia and the inflammatory response have not been thoroughly explored." (PMID 36204568, 2022). "Increasing evidence has shown that certain stimuli, such as oxidized low-density lipoprotein, hyperglycemia, and nicotine, can activate the NLRP3 inflammasome in EC, thus leading to endothelial cell death." (PMID 36389728, 2022).
Hyperglycemia (continued). "Hyperglycemia, hyperlipidemia, and hyperuricemia can all activate the NLRP3 inflammasome, and NLRP3 knockout (KO) can attenuate glomerular hypertrophy, glomerulosclerosis, and mesangial matrix expansion in streptozotocin (STZ)-induced diabetic mice." (PMID 36304156, 2022). "It has been reported that hyperglycemia activates NLRP3 inflammasome, thus promoting pro-caspase-1 to caspase-1." (PMID 35034587, 2022). "The Akimba mouse model, which is characterized by hyperglycemia, inflammation, and advanced DR vascular lesions also demonstrates significantly higher expression of NLRP3, ASC and caspase-1 compared to wild-type mice." (PMID 36430950, 2022). "The available evidence suggests that hyperglycemia can promote the deposition of collagen in muscle, which leads to fibrosis, and the excessive activation of the NLRP3 inflammasome contributes to tissue fibrosis." (PMID 35563208, 2022). "Sustained hyperglycemia and hyperlipidemia can stimulate ROS overproduction, and consequently leading to downstream NLRP3 inflammasome aggregation and activation in cardiomyocytes." (PMID 34631209, 2021). "NLRP3 (NOD-, LRR-, and pyrin domain-containing protein 3) is an intracellular sensor, that can result in activation of NLRP3 inflammasome due to diverse stimuli such as hyperglycemia and ROS and then leading to caspase-1 activation." (PMID 34205870, 2021). "Our previous studies proved that the NLRP3 inflammasome mediated by hyperglycaemia is the core mechanism of endothelial dysfunction." (PMID 34180143, 2021). "Previous studies have confirmed that hyperglycemia induced NLRP3 inflammasome activation, while the active caspase-1 induces excessive release of inflammatory cytokines, leading to tight junction disruption and consequent endothelial permeability." (PMID 34631209, 2021). "A study demonstrated that Sirt1 inhibits hyperglycemia-induced renal inflammation by negatively regulating the NLRP3 inflammasome in DM." (PMID 35096293, 2021). "UCP2 is likely an upstream mediator of ROS generation and NLRP3 inflammasome activation in hyperglycemia-exacerbated I/R damage." (PMID 33735403, 2021). "Hyperglycemia can trigger NLRP3 overactivation and promote the production of cleaved caspase-1, thus accelerating the maturation and release of IL-1β and IL-18, which induce pyroptosis and finally lead to cardiac dysfunction and heart failure." (PMID 35096293, 2021). "Saturated fatty acids, pro-inflammatory adipokines, excess ATP, reactive oxygen species (ROS), hyperglycemia and other metabolic insults serve as major inducers of a cycle of NLRP3 inflammasome activation and cytokine production." (PMID 34362072, 2021). "This study illustrated that hyperglycemia-induced NLRP3 inflammasome is involved in the EC dysfunction." (PMID 35145423, 2021). "Hyperglycemia activates the NLRP3 inflammasome, accompanied by TXNIP activation, which inhibits the expression of thioredoxin." (PMID 33637069, 2021). "Our results demonstrated that kakonein protects against hyperglycaemia‐induced endothelial dysfunction by restoring endothelial autophagy to degrade the NLRP3 inflammasome." (PMID 34180143, 2021). "Naringin reduces hyperglycemia, inhibits the proliferation of cells induced by high glucose, and decreases the expression of inflammatory that is mediated by NLRP3 through the NLRP3-caspase-1-IL-1β/IL-18 signaling pathway." (PMID 34371645, 2021). "Hyperglycaemia can stimulate NLRP3 inflammasome activation in human adipose tissue by upregulating the expression of TXNIP." (PMID 33435142, 2021). "Meanwhile, induction of autophagy leading to inactivation or selective clearance of the NLRP3 inflammasome regulates vascular disease in hyperglycaemia." (PMID 34180143, 2021). "It has been shown that RNA MALAT1 can inhibit miR-23c expression and promote hyperglycemia-induced pyroptosis of renal tubular epithelial cells by inhibiting miR-30c via the activation of NLRP3." (PMID 34007404, 2021).